NOVA1 (NOVA alternative splicing regulator 1)
Description:
RNA-binding protein which regulates alternative splicing of pre-mRNAs in the brain and spinal cord in a sequence-specific manner (By similarity). Binds to 5'-YCAY-3' repeats, with a minimum of 2 to 3 repeats necessary for high-affinity binding. Mediates both exon inclusion and exclusion, depending upon the position of its binding site within the pre-mRNA. Binding to 5'-YCAY-3' clusters results in a local and asymmetric action to regulate spliceosome assembly. Binding to an exonic 5'-YCAY-3' cluster changes the protein complexes assembled on pre-mRNA, blocking U1 small nuclear ribonucleoprotein (snRNP) binding and inhibiting exon inclusion, whereas binding to an intronic 5'-YCAY-3' repeat enhances spliceosome assembly and favors exon inclusion (By similarity). Regulates the splicing of gamma-aminobutyric acid receptor subunit gamma-2 (GABRG2) and glycine receptor subunit alpha-2 (GLRA2) pre-mRNAs, among others (By similarity). Autoregulates its own splicing. Binds to its own exon 4 and directs its exclusion, thus leading to NOVA1 isoform 3 production (By similarity). May affect the splicing of many genes involved in vocal behavior (By similarity).
Synonyms: NOVA-1
Tractability: PROTAC: its protein half-life has been measured.
Gene: Protein-coding gene on chromosome 14 (26,443,090 to 26,598,033, reverse strand). Ensembl gene ENSG00000139910.
Subcellular location: Nucleus
Subcellular location (Human Protein Atlas): Nucleoli; Nucleoplasm
Gene Ontology:
Molecular function: protein binding; RNA binding; sequence-specific mRNA binding; mRNA binding; mRNA 3'-UTR binding; nucleic acid binding
Biological process: mRNA splicing, via spliceosome; negative regulation of cold-induced thermogenesis; nervous system development; regulation of alternative mRNA splicing, via spliceosome; RNA processing; RNA splicing
Cellular component: nucleolus; nucleoplasm; nucleus
Genetic constraint (gnomAD): Loss-of-function variants: 7 observed, 34.81 expected, observed/expected ratio (o/e) 0.2, 90% interval 0.11 to 0.38. The upper end of that interval is the gene's LOEUF score, 0.38, which puts it in group 1 of 6, group 1 being the genes least tolerant of losing a copy. Missense variants: 426 observed, 591.18 expected, observed/expected ratio (o/e) 0.72, 90% interval 0.67 to 0.78. Synonymous variants: 260 observed, 222.9 expected, observed/expected ratio (o/e) 1.17, 90% interval 1.05 to 1.29.
Homologues: Orthologues: chimpanzee NOVA1 (99% identical), macaque NOVA1 (99% identical), pig NOVA1 (99% identical), rabbit NOVA1 (99% identical), guinea pig NOVA1 (99% identical), mouse Nova1 (99% identical), tropical clawed frog nova1 (97% identical), dog NOVA1 (95% identical), rat Nova1 (95% identical), zebrafish nova2 (79% identical), zebrafish nova1 (78% identical), Drosophila melanogaster ps (44% identical), and 7 more. Paralogues in human: NOVA2 (72% identical), FUBP1 (23% identical), KHSRP (21% identical), FUBP3 (20% identical), PCBP3 (18% identical), HNRNPK (17% identical), PCBP4 (17% identical), PCBP2 (17% identical), IGF2BP2 (16% identical), IGF2BP1 (16% identical), PCBP1 (16% identical), IGF2BP3 (14% identical).
Diseases named in the same sentence as NOVA1 in open-access papers:
NOVA1 is named in the same sentence as 45 diseases in open-access papers, as found by Europe PMC text mining. Sharing a sentence is not in itself a finding about the gene and the disease. The quoted sentences say what the papers report.
hepatocellular carcinoma (10 papers, 2014 to 2023). A malignant tumor that arises from hepatocytes. "High expression of the NOVA1 RNA-binding protein has been found to be associated with unfavorable prognosis in hepatocellular carcinoma." (PMID 25923053, 2015). "At the same time, MALAT1 regulates the miR-3129-5p/Nova1 axis to reduce the sensitivity of hepatocellular carcinoma to adriamycin." (PMID 36793374, 2023). "Intratumoral Nova1 has been reported to be strongly correlated with hepatocellular carcinoma (HCC) poor survival and increased early recurrence." (PMID 37875914, 2023). "In line with this, the putative targets of miR-146b-5p including TRAF6 and NOVA1 have been shown to increase chemoresistance in OSCC and hepatocellular carcinoma, respectively." (PMID 36703917, 2022). "Neuro-oncological ventral antigen 1 (Nova1) is a neuron-specific RNA-binding protein in human paraneoplastic opsoclonus-myoclonus ataxia accompanying with malignant tumors, but its role in hepatocellular carcinoma (HCC) remains elusive." (PMID 24608171, 2014). "For instance, RNA-binding protein Nova1 and NELFE promote cancer growth in hepatocellular carcinoma (HCC) cells, whereas RBM47 and RBM43 have been shown to suppress HCC growth." (PMID 34434291, 2021). "The mechanism of Nova1’s role in hepatocellular carcinoma has not been delineated." (PMID 27733149, 2016).
gastric cancer (9 papers, 2016 to 2025). A primary or metastatic malignant neoplasm involving the stomach. "Some studies have shown that the expression of neuro-oncological ventral antigen 1(NOVA1), a marker of CAFs, is downregulated in the gastric cancer TME, and its downregulation is associated with an increase in M2 macrophages." (PMID 40485724, 2025). "MiR-27a-3p regulates the expression of NOVA1 to control epithelial-mesenchymal transition in gastric cancer." (PMID 35348441, 2022). "NOVA1 is also overexpressed in gastric cancer with the downregulation of miR-339, another miRNA that directly targets the Nova1 3′UTR." (PMID 34769047, 2021). "The results showed that DAZ1, WIPF3, RBPMS2, and NOVA1 were low expressed in gastric cancer (P<0.05), and KIAA0101 and COL5A2 were highly expressed (P<0.05)." (PMID 34234866, 2021). "Among these splicing factors, TIA1 and NOVA1 have been proven to promote gastric cancer development via regulating AS." (PMID 33281863, 2020). "In addition, miR-146b-5p directly targets Nova1, and its upregulation was observed in tissues surrounding the sites of tumors in gastric cancer after gastrectomy." (PMID 34769047, 2021). "In addition, decreased NOVA1 expression in stromal fibroblasts and spindle cells of the gastric cancer field was related to poor patient prognosis." (PMID 26673617, 2016). "Kim et al25 demonstrated that suppressed expression of NOVA1 was found in the gastric cancer (GC) microenvironment, and down‐regulated expression of NOVA1 in GC cells was correlated with GC progression and poor prognosis." (PMID 29498217, 2018). "Contradictory to other studies, repression of NOVA1 by the overexpression of miR-27a-3p, which directly targets the Nova1 3′UTR, has been identified in gastric cancer." (PMID 34769047, 2021). "In contrast, NOVA1 is considered to be an oncogene and a prognostic factor in multiple malignant tumors, including CRC, thyroid cancer, breast cancer, melanoma, osteosarcoma, and gastric cancer." (PMID 35832652, 2022).
lung carcinoma (7 papers, 2015 to 2023). "We examined the expression of Nova1 in four lung cancer cell lines and in a normal bronchial epithelial cell line (HBE)." (PMID 36284263, 2022). "Abnormal expression of QKI and NOVA1 has been reported to participate in the development of lung cancer and colorectal cancer." (PMID 32939931, 2020). "This indicates that NOVA1 knockdown in H920 cells significantly altered the ability of these lung cancer cells to form tumors in vivo." (PMID 30082712, 2018). "For example, the β-deletion has been shown or speculated to be regulated by RMB10 in pancreatic cancer; NOVA1/PTBP1 in lung cancer; SRSF11, hnRNPH2, and hnRNPL in breast cancer; and MCPH1/BRIT1 in ovarian cancer." (PMID 33924498, 2021). "Among the classifier genes that are up-regulated in lung cancer, NOVA1 and CDR1 are predominantly expressed in neurons, but are also expressed in tumors and are associated with para-neoplastic antibodies in several malignancies, including small-cell lung cancer." (PMID 25944280, 2015). "Thus, NOVA1 acts as an oncogene in lung cancers by activating the Wnt signaling pathway." (PMID 36284263, 2022). "NOVA1 (NOVA alternative splicing regulator 1), a well-known regulator of alternative splicing first identified in lung cancer cells, modulates pre-mRNA splicing in genes related to neuronal function and cancer progression." (PMID 37924098, 2023). "NOVA1 protein was not expressed in normal human bronchial epithelial cells (HBECs), and was overexpressed in 71% of our lung cancer cell lines (12 of 17 lines)." (PMID 30082712, 2018).
breast carcinoma (6 papers, 2014 to 2022). "In contrast, tumors with an hPRLrIlo/hPRLrLhi ratio were enriched in genes associated with luminal breast cancer (e.g., CGA, PVALB, NOVA1), and were more likely to be small in size and early stage." (PMID 33772010, 2021). "Neuro-oncological ventral antigen 1 (Nova1) was first identified as a neuron-specific RNA binding protein in paraneoplastic opsoclonus-myoclonus ataxia (POMA), which is associated with breast cancer, fallopian cancer and small cell lung cancer." (PMID 24608171, 2014).
melanoma (4 papers, 2018 to 2024). A malignant, usually aggressive tumor composed of atypical, neoplastic melanocytes. "Our result showed that the expression of NOVA1 in melanoma was overexpressed in all three patients with melanoma compared to that in two cases of cutaneous nevus." (PMID 29498217, 2018). "In addition, we demonstrated that the expression of NOVA1 was up‐regulated in melanoma cell lines (A875, A375 and SK‐MEL‐1) compared to normal melanocyte cell line (D78) using Western blot and qRT‐PCR." (PMID 29498217, 2018). "In addition, we indicated that inhibited expression of NOVA1 suppressed melanoma cell growth, migration and invasion." (PMID 29498217, 2018). "Moreover, we demonstrated that knockdown of NOVA1 suppressed melanoma cell proliferation, migration and invasion in both A375 and A875 cell lines." (PMID 29498217, 2018). "Moreover, we demonstrated that knockdown of NOVA1 suppressed melanoma cell proliferation, migration and invasion partly through regulating FoxO3A expression." (PMID 29498217, 2018). "In line with this, NOVA1 mRNA was also detected in three melanoma tissues." (PMID 29498217, 2018). "Our data showed that NOVA1 protein was expressed in three melanoma samples." (PMID 29498217, 2018). "In addition, we showed that suppressed expression of NOVA1 enhanced forkhead box O3a (FOXO3a) expression while inhibited AKT expression in melanoma cell." (PMID 29498217, 2018). "NOVA1 acts an oncological role in melanoma, and knockdown may provide a novel therapeutic target for melanoma." (PMID 29498217, 2018). "Moreover, we demonstrated that knockdown of NOVA1 suppressed melanoma cell proliferation, migration and invasion in both A375 and A875 cells." (PMID 29498217, 2018). "In particular, knockdown of NOVA1 and TRIB2 has been shown to inhibit melanoma cell proliferation, migration, and invasion partly through promoting nuclear translocation of FoxO3a." (PMID 34418600, 2021). "In addition to CSDE1, several RBPs have been shown to play roles in melanoma progression, including CELF, CPEB4, IGF2BP1, IGF2BP3, NOVA1 and DDX3X, among others." (PMID 38396995, 2024). "Also, NOVA1 (RNA-binding proteins) and tribbles pseudokinase 2 (TRIB2) (mammalian homolog of the Drosophila gene tribbles) have been shown to contributes to the maintenance of the malignant phenotype of melanoma cells through inhibition of FoxO3a activity." (PMID 34418600, 2021).
astrocytomas (3 papers, 2015 to 2017). "They identified RNA binding protein NOVA-1 (NOVA1) to be a marker distinguishing astrocytoma with oligodendrogliomas and heat shock protein beta 1 (HSPB1) as a predictive marker for poor prognosis for GBM15." (PMID 27246909, 2016). "RNA binding protein nova 1 (NOVA1) presented an interesting expression profile when low grade astrocytomas and oligodendrogliomas grade II were compared (p = 0.0082)." (PMID 26108672, 2015). "Expression level of RNA binding protein nova 1 (NOVA1) differentiated low-grade oligodendroglioma and astrocytoma grade II (p = 0.0082)." (PMID 26108672, 2015).
non-small cell lung carcinoma (3 papers, 2018 to 2023). A group of at least three distinct histological types of lung cancer, including non-small cell squamous cell carcinoma, adenocarcinoma, and large cell carcinoma. "More recently we have identified a role for the splicing factor NOVA1 in binding to DR8 and promoting FL telomerase splicing and activity in non-small cell lung cancer cells." (PMID 30568224, 2019).
small cell lung carcinoma (3 papers, 2014 to 2022). Small cell lung cancer (SCLC) is a highly aggressive malignant neoplasm, accounting for 10-15% of lung cancer cases, characterized byrapid growth, and early metastasis. "Previous studies have found that high expression of Nova1 is closely associated with poor survival in small cell lung cancer patients and has served as a promising predictive factor for prognosis in this disease." (PMID 36284263, 2022).
cardiac hypertrophy (2 papers, 2022 to 2024). "We further demonstrated that miR-27a-3p promoted cardiac hypertrophy through regulating NOVA1 expression." (PMID 35348441, 2022). "To further corroborate the role of miR-27a-3p/NOVA1 axis in cardiac hypertrophy, we treated H9c2 cells with Ang II, in the presence of miR-27a-3p inhibitor and NOVA1 siRNA." (PMID 35348441, 2022). "In addition, the upregulation of miR-27a-3p promotes cardiac hypertrophy by targeting NOVA1 (neurooncological ventral antigen 1)." (PMID 39850481, 2024). "In addition, in both animal model and cell model of cardiac hypertrophy, we showed the reduced expression of NOVA1." (PMID 35348441, 2022). "In summary, these results suggest that the upregulation of miR-27a-3p may serve as a diagnostic factor for cardiac hypertrophy, and miR-27a-3p upregulation promotes cardiac hypertrophy by targeting NOVA1." (PMID 35348441, 2022). "Therefore, NOVA1 is a target of miR-27a-3p involved in cardiac hypertrophy regulation." (PMID 35348441, 2022). "We aimed to investigate the expression pattern and functional role of miR-27a-3p in Ang II-induced cardiac hypertrophy, identify the downstream target of miR-27a-3p, and determine whether the miR-27a-3p/NOVA1 axis regulates the progression of Ang II-induced cardiac hypertrophy." (PMID 35348441, 2022).
diabetes (2 papers, 2021 to 2022). "Besides Srrm4, the expression of two other neuron-specific splicing factors, Nova1 and Rbfox2, as well as the diabetes gene Glis3, which regulates splicing of Bim3, encoding an apoptosis protein, is lower in NZO than in B6-ob/ob islets." (PMID 34445304, 2021). "Both in vitro and in in vivo studies have previously shown that Bim is downstream Nova1 and plays an important role in β-cell apoptosis in diabetes." (PMID 36145242, 2022). "A limitation of our studies is that we focused our in vivo work on adult male mice, but the role of Nova1 and Bim in β-cell function should also be clarified in the development of obesity and diabetes at different ages and in females." (PMID 36145242, 2022). "β-cell-specific Nova1 or Bim deficiency failed to affect diabetes development in response to MLD-STZ-induced β-cell dysfunction and death evidenced by unaltered blood glucose levels and pancreatic insulin content." (PMID 36145242, 2022). "Next, to test our hypothesis that Nova1 deletion exacerbates the impaired glucose tolerance in diabetes, we subjected βNova1−/− and littermate control mice to a model of inflammatory-mediated diabetes by injecting MLD-STZ and followed the glycemia, body composition, and body weight." (PMID 36145242, 2022). "Thus, Nova1 or Bim deletion in β-cells does not impact on glucose homeostasis or diabetes development in mice." (PMID 36145242, 2022).
epilepsy (2 papers, 2016 to 2022). A brain disorder characterized by episodes of abnormally increased neuronal discharge resulting in transient episodes of sensory or motor neurological dysfunction, or psychic dysfunction. "There was no apparent phenotype in Nova2 heterozygotes, although we previously found that when assessed by electroencephalography, 6 month old Nova2+/- (and Nova1+/-) mice had frequent synchronous cortical interictal discharges consistent with epilepsy." (PMID 27223325, 2016). "Notably, upregulation of NOVA1, neuroLSD1, and of the IEG proteins NR4A1, EGR1, and NPAS4 has been observed in patients with epilepsy and/or in epileptic mouse models, and their deregulation might contribute to DEE9 epileptic phenotype." (PMID 35613587, 2022).
glioma (2 papers, 2022 to 2023). A benign or malignant brain and spinal cord tumor that arises from glial cells (astrocytes, oligodendrocytes, ependymal cells). "Our study found that genes involved in AS events affected glioma survival including NOVA1, HNRNPC, HNRNPLL, RBM4." (PMID 35832652, 2022). "We demonstrated that NOVA1, HNRNPC, HNRNPLL, and RBM4 were independent prognostic factors for glioma, and their expression was verified by western blotting analysis." (PMID 35832652, 2022).
liver cancer (2 papers, 2014 to 2022). An epithelial or non-epithelial malignant neoplasm that arises from the liver. "All these study shed a light on the potential diagnostic value of Nova1 in liver cancer development." (PMID 24608171, 2014). "In brief, it is reported in the present study that Nova1 exists in liver cancer cells." (PMID 24608171, 2014).
autoimmune neurologic disease (1 paper, 2014). "NOVA1 belongs to the Nova family of neuron-specific RNA-binding proteins, which were originally identified as targets in an autoimmune neurologic disease characterized by the failure of motor inhibition." (PMID 25299073, 2014).
carcinoids (1 paper, 2023). "The presence of the selected splicing factors in carcinoids was further examined by IHC analysis, which confirmed that the protein of three splicing factors, NOVA1, PRPF8 and SRSF10 was detectable in tissue samples." (PMID 38049848, 2023). "Inasmuch as the primary known role for NOVA1, PRPF8 and SRSF10 is their function as splicing factors, we aimed at examining their putative relationship with the alternative splicing profile in carcinoid cells." (PMID 38049848, 2023).
head and neck squamous cell carcinoma (1 paper, 2021). A squamous cell carcinoma that arises from any of the following anatomic sites: lip and oral cavity, nasal cavity, paranasal sinuses, pharynx, larynx, and salivary glands. "Three RBP genes (NOVA1, EZH2, and RBM24) were identified as central genes related to the prognosis of head and neck squamous cell carcinoma (HNSCC)." (PMID 33711033, 2021).
HIV-1 infection (1 paper, 2013). The type species of lentivirus and the etiologic agent of acquired immunodeficiency syndrome (AIDS). "What could be the role of TOX4 and NOVA1 during HIV-1 infection?" (PMID 24312278, 2013).
Insulin resistance (1 paper, 2022). Increased resistance towards insulin, that is, diminished effectiveness of insulin in reducing blood glucose levels. "Therefore, we challenged Nova1 deficient β-cells with inflammatory stress (MLD-STZ) or moderate metabolic stress (insulin resistance) conditions." (PMID 36145242, 2022). "To further understand the impact of Nova1 deletion in a model of moderate β-cell stress, we induced metabolic stress (obesity and insulin resistance) by feeding the mice a high-fat diet for 12 weeks." (PMID 36145242, 2022).
lung carcinoids (1 paper, 2023). "In summary, our work primarily unveils a clear alteration of the splicing machinery in lung carcinoids that is linked to three specific factors, NOVA1, PRPF8 and SRSF10, which are differentially associated to pathological features, distinct profiles of splicing events, and key functional actions." (PMID 38049848, 2023).
mental retardation (1 paper, 2008). "With the exception of FMRP, Dazla, and Nova-1, which are associated with mental retardation, azospermia, and neuronal viability respectively, the majority of the mammalian RNA binding proteins are constitutively expressed and exhibit a relative broad RNA-binding specificity." (PMID 19094237, 2008).